LOXL2 (lysyl oxidase like 2)
Diseases named in the same sentence as LOXL2 in open-access papers (continued):
Sharing a sentence is not in itself a finding about the gene and the disease.
pulmonary fibrosis (continued). "Studies demonstrating therapeutic efficacy of a LOXL2-specific antibody in experimental lung fibrosis models point towards a prominent role of LOXL2 in fibrotic remodeling." (PMID 28273952, 2017). "In fact, LOXL2 inhibition alone may be sufficient to alleviate mild to medium levels of pulmonary fibrosis in animal models and human IPF patients." (PMID 35628342, 2022). "In addition, they also found increased expression of Loxl2, Loxl3, and Loxl4 in whole lung tissue from pulmonary fibrosis mouse models using gene expression assays at day 14 post-bleomycin." (PMID 34395518, 2021). "Indeed, a monoclonal antibody against LOXL2 was reported to ameliorate experimental pulmonary fibrosis, and humanized IgG4 monoclonal antibody against LOXL2 is under development as a new antifibrotic treatment." (PMID 32046322, 2020). "Studies in a bleomycin-induced pulmonary fibrosis model strongly suggested that LOXL2 was an attractive target in fibrosis and lead to a clinical trial designed to investigate the efficacy and safety of Simtuzumab, a monoclonal antibody against LOXL2, in patients with IPF." (PMID 38873180, 2023). "The effects of LOXL2 on lung fibroblast proliferation and fibrosis development in mice with bleomycin (BLM)-mediated pulmonary fibrosis and the association of LOXL2 in the advancement of pulmonary fibrosis via the TGF-β1/Smad signaling pathway have not been adequately studied." (PMID 37275755, 2023). "In addition, the development and progression of pulmonary fibrosis is influenced by LOXL2, and LOX may be connected to the TGF-β signaling pathway." (PMID 37275755, 2023). "In our study, we therefore excluded patients with factors that may affect LOXL2, such as HF, tumors, and pulmonary fibrosis, and found that LOXL2 was significantly higher in patients with AF than those without AF, indicating that LOXL2 may be involved in the pathogenesis of AF." (PMID 29089463, 2017). "Indeed, LOXL2 inhibition prevented and even reversed bleomycin-induced pulmonary fibrosis in mice." (PMID 29125826, 2017). "Recently, inhibitors of TGFβ (1D11), PDGF (Nintedanib), AKT (triciribine), galectin-3 (TD139), LPA-1 (AM966), and LOXL2 (AB0023) have shown promising and beneficial effects in rodent models of lung fibrosis." (PMID 38534359, 2024). "Recently, both LOXL2 and LOXL3 were identified to be crucial for fibroblast-to-myofibroblast transition in in vitro models of lung fibrosis." (PMID 29966587, 2018). "Selective LOXL2/LOXL3 inhibition reduces fibrosis and improves lung function in an in vivo model of lung fibrosis driven by TGF-β." (PMID 29966587, 2018). "In fibrotic diseases, such as pulmonary fibrosis, persistent TGF‐β1 signaling activates α‐smooth muscle actin positive (α‐SMA+) myofibroblasts, which deposit stiff collagen I. LOXL2‐mediated collagen crosslinking generates irreversible fibrils resistant to MMP cleavage." (PMID 40686923, 2025). "The targeting of LOXL2 in vivo further indicated that this enzyme was not required for the development of pulmonary fibrosis in this model." (PMID 38873180, 2023). "Regardless of the issues associated with targeting LOXL2 in pulmonary fibrosis, caution is certainly warranted as biotech and pharmaceutical Companies proceed with other targeting approaches toward LO and LOX and simply rely on preclinical data from bleomycin-induced pulmonary fibrosis models." (PMID 38873180, 2023).
gastric cancer (30 papers, 2013 to 2025). A primary or metastatic malignant neoplasm involving the stomach. "Further, LOXL2 expression both in cancer cells and associated stromal fibroblasts has been shown to correlate with metastasis and poor survival in gastric cancer." (PMID 30701028, 2018). "While untreated conditioned medium increased the migration and invasion, LOXL2 siRNA treatment of cancer-associated fibroblasts significantly decreased the migration and invasion of gastric cancer cells, underlining the tumor promoting role of LOXL2 in tumor-associated stroma cells." (PMID 30473751, 2018). "A study in gastric cancer biopsies shows that the expression of the TRIM44 protein is inversely correlated with the expression of LOXL2." (PMID 40906383, 2025). "This study shows that TRIM44 regulates the stability of LOXL2 and thus modulates the ability of LOXL2 to remodel the extracellular matrix in gastric cancer." (PMID 40906383, 2025). "Secreted LOXL2 was also a novel therapeutic target that promoted gastric cancer metastasis via the FAK pathway." (PMID 38291516, 2024). "Specifically, TRIM44 mediated the ubiquitination and subsequent degradation of Lysyl Oxidase Like 2 (LOXL2), thus impacting extracellular matrix remodeling and influencing tumor immunity in gastric cancer." (PMID 39768197, 2024). "They suggest the TRIM44/LOXL2 complex as a potential biomarker for gastric cancer prognosis and as a novel immunotherapy target." (PMID 37296972, 2023). "Targeting LOXL2 in decreasing tumor cell growth and metastasis has been well-documented in various tumors such as gastric cancer, pancreatic cancer, and cervical cancer." (PMID 36555612, 2022). "The analysis of various gastric cancer cell lines and gastric cancer patient samples also revealed a positive association between ELK3 and BMP1, LOXL2, SNAI1, SERPINF1, DCN, and NID1, and these genes were associated with a poor prognosis." (PMID 35409069, 2022). "The analysis of data from TCGA and GTEx revealed that ELK3 and BMP1, and LOXL2 were highly expressed in the gastric cancer samples compared with the healthy samples." (PMID 35409069, 2022). "Silencing of LOXL2 in cancer cells led also to a decrease of invasiveness in pancreatic and gastric cancer in vitro models." (PMID 30473751, 2018). "Conditioned medium from fibroblasts, which were extracted from the gastric wall of diffuse-type gastric carcinoma patients and transfected with LOXL2 siRNA, was co-cultured with gastric cancer cells." (PMID 30473751, 2018). "An earlier report showed that secreted LOXL2 positively modulate the FAK/Src signaling pathways in gastric carcinoma cells." (PMID 24414204, 2014). "LOXL2 silencing in pancreatic cancer cells has shown improved sensitivity to gemcitabine therapy and decreased tumor growth in gastric cancer." (PMID 24007603, 2013). "In gastric cancer, LOXL2 facilitates cancer cell metastasis through activating Src/FAK pathway." (PMID 34308761, 2021). "We speculate that LOX and LOXL2 affect the occurrence and development of gastric cancer by participating in the regulation of extracellular matrix, but further research is still needed." (PMID 35126449, 2021). "The findings of previous studies have shown that LOXL2 is highly expressed in a variety of cancers in humans including head and neck squamous cell carcinoma, breast, colon, skin, and gastric cancer, and its high expression correlates with metastasis and poor prognosis." (PMID 31086173, 2019). "Several studies have reported changes in LOX, LOXL1, LOXL2, LOXL3, and LOXL4 expression in gastric cancer." (PMID 40906383, 2025). "In gastric cancer, it has been shown that TRIM44, an E3 ubiquitin ligase, regulates the stability of the LOXL2 protein, a key factor for crosslinking collagen and important for remodeling the ECM, thus regulating tumor immunity." (PMID 37296972, 2023).
gastric cancer (continued). "The gene analysis of samples from patients with gastric cancer indicated that a high ELK3 expression is positively correlated with BMP1, LOXL2, SNAI1, SERPINF1, DCN, and NID1 expression, all of which are closely associated with a poor prognosis." (PMID 35409069, 2022). "First, the correlation between ELK3 expression and BMP1, LOXL2, SNAI1, SERPINF1, DCN, and NID1 expression was analyzed in 19 different gastric cancer cell lines." (PMID 35409069, 2022). "Patients with gastric cancer with a high expression of BMP1, LOXL2, SNAI1, SERPINF1, DCN, and NID1 had a poor prognosis." (PMID 35409069, 2022). "Similarly, in gastric cancer, LOXL2 has been shown to activate the FAK/Src pathway, thereby facilitating the metastasis of gastric cancer cells." (PMID 39247609, 2024). "The ELK3 expression in gastric cancer cells and human gastric cancer samples positively correlated with that of BMP1, LOXL2, SNAI1, SERPINF1, DCN, and NID1, suggesting that this gene signature may be predictive molecular markers for aggressive gastric cancer progression." (PMID 35409069, 2022). "Notably, the analysis of patients with gastric cancer indicated the marked positive regulation of ELK3 and BMP1, LOXL2, SNAI1, SERPINF1, DCN, and NID1 gene expression, suggesting a significant positive correlation between ELK3 and ECM remodeling-associated genes in gastric cancer." (PMID 35409069, 2022). "Additionally, to investigate the clinical relevance of the target gene expression in gastric cancer, we examined their expression levels at different stages of TCGA gastric cancer samples and observed significantly higher expression of SERPINE1, COL5A2, SEMA3C and LOXL2 in more aggressive stages." (PMID 36307405, 2022).
lung carcinoma (30 papers, 2016 to 2025). "Downregulation of miR-29a is associated with posttranslational overexpression of LOXL2 in lung cancer, promoting tumor progression through modulating ECM stiffness." (PMID 37468874, 2023). "LOXL2 (lysyl oxidase like 2), an enzyme involved in collagen crosslinking, is known to promote tumor invasiveness and metastasis through extracellular matrix remodeling and has been linked to poor outcomes in various tumors, including lung cancer." (PMID 41395115, 2025). "LOXL2 was shown by Fan and colleagues to promote lung cancer metastasis and progression via CEBPA‐mediated upregulation, which inhibits BCL‐2 degradation." (PMID 41395115, 2025). "To examine the influence of LOXL2 on cellular senescence in tumors, we performed β-galactosidase (SA-β-gal) staining and real-time quantitative PCR assays in lung cancer and liver cancer cells." (PMID 38922489, 2024). "In a model of collagen-dependent lung cancer metastasis, trihydroxyphenolics blocked collagen deposition by inhibiting LOXL2." (PMID 37468874, 2023). "In lung cancer cells, the downregulation of LOXL2 thickens the cell surface glycocalyx, which facilitates the formation of cell clusters and thus enhances the invasion and migration of tumor cells." (PMID 36293126, 2022). "A pro-metastatic function of LOXL2 in murine lung cancer cells that have undergone EMT has been attributed to its role in collagen stabilization and activation of integrin signaling." (PMID 29503225, 2018). "Furthermore, ZEB1 promotes the invasive behavior of lung cancer by stabilizing and depositing collagen mediated by LOXL2 in the extracellular matrix." (PMID 41252548, 2025). "Upregulation of LOXL2 enhanced the invasion and metastasis of lung cancer." (PMID 36186418, 2022). "Upregulation of LOXL2 has been shown to promote lung cancer invasion and metastasis." (PMID 34552612, 2021). "Therefore, mechanistically validating LAIR1 and SHP-1 as additional therapeutic targets in combination with PD-1/PD-L1 blockade is vital to circumvent the need for early LOXL2 inhibition and to allow treatment of lung cancer patients with late-stage disease." (PMID 32908154, 2020). "The four genes, GREM1, LOXL2, ADAMTS12 and ITGA11, provide a candidate stromal signature that may be functionally implicated in lung cancer dissemination." (PMID 29503225, 2018). "Knockdown of LOXL2/LOXL3 inhibits EMT, proliferation, migration, and invasion, while promoting apoptosis in lung cancer cells." (PMID 41250755, 2025). "Knockdown of LOXL2/LOXL3 can inhibit EMT, cell proliferation, migration, and invasion processes, while also enhancing the apoptosis of lung cancer cells." (PMID 41250755, 2025). "In summary, LOXL2 and LOXL3 are highly expressed in lung cancer and influence tumor prognosis by modulating immune infiltration." (PMID 41250755, 2025). "In lung cancer, CEBPA enhances the transcriptional expression of LOXL2/LOXL3 and stabilizes BCL-2, thereby promoting the initiation and progression of lung cancer." (PMID 41250755, 2025). "CEBPA can recruit Tip60, thereby enhancing the transcription of LOXL2 and LOXL3 and the histone acetylation process in lung cancer cells." (PMID 41250755, 2025). "JMJD2C reduces the level of trimethylation on the histone H3 at lysine 9 (H3K9), and activate the genes lysyl oxidase-like protein 2 (LOXL2) and L1 cell adhesion molecule (L1CAM) that can promote lung cancer metastasis." (PMID 33109235, 2020). "Altogether our data suggest that expression of GREM1, LOXL2, ITGA11 and ADAMTS12 by MSCs enhances primary lung cancer metastasis." (PMID 29503225, 2018). "Our previous studies have shown that restoration of the miR-29 family significantly inhibits cancer cell aggressiveness through targeting lysyl oxidase like-2 (LOXL2) in HNSCC, renal cell carcinoma, and lung cancer." (PMID 29423074, 2018).
lung carcinoma (continued). "Finally, CEBPA binds to Tip60 to promote the transcription of LOXL2 and LOXL3, thereby enhancing the stability of BCL-2 and ultimately promoting the development and metastasis of lung cancer cells." (PMID 41250755, 2025). "For cancer treatment, ablation LOXL2 restores cancer cells RS, increases intratumoral CD8+ T cell infiltration, declines exhausted CD8+ T cells, thus reducing tumor burden and resensitizing anti-PD-L1 resistant lung cancer cells." (PMID 38977778, 2024). "In lung cancer, a study reported that HIF1A could mediate the immunosuppressive by the HIF1A/LOXL2/EMT pathways, and our results also showed that COPZ1 had a positive correlation with HIF1A, LOXL2 and EMT." (PMID 37107648, 2023). "For instance, MSCs derived from normal lung tissue stimulated by TME are transformed into TA-MSCs expressing high levels of gremlin 1 (GREM1), lysyl oxidase-like 2 (LOXL2), integrin α 11 (ITGA11), which promote invasion and metastasis of lung cancer cells via stromal pro-metastatic signaling." (PMID 35842634, 2022). "Studies on the extracellular effect of LOXL2 have revealed that the MiR200/Zinc finger E-box-binding homeobox 1(ZEB1) induces LOXL2-mediated collagen stabilization and deposition in TME, which can activate the ITG-β1/FAK/Src pathway in lung cancer cells and promote tumor invasion and metastasis." (PMID 36293126, 2022). "Metastatic lung cancer has been shown to have increased linearity of collagen fibers and organization that correlated with increased expression of the lysyl oxidases, LOX and LOXL2." (PMID 31121900, 2019). "Similarly, miR-504 is downregulated in non–small cell lung cancer tissue and inhibits cell proliferation, invasion, and EMT by targeting LOXL2 (lysyl oxidase–like 2)." (PMID 31419987, 2019).
pancreatic cancer (29 papers, 2013 to 2025). "Loxl2 has been identified as an independent prognostic factor in pancreatic cancer patients associated with poor survival." (PMID 37156840, 2023). "These clinical and preclinical data confirm that higher LOXL2 expression is associated with the invasiveness of pancreatic cancer cells and the low survival rate of pancreatic cancer patients." (PMID 27285767, 2016). "Additionally, higher LOXL2 expression levels in pancreatic cancer were associated with a significantly greater potential for distant metastasis." (PMID 38560567, 2024). "Therefore, in this present study, we investigated whether N-WASP expression is associated with LOXL2 by examining the development of pancreatic cancer using in vitro and in vivo models." (PMID 38560567, 2024). "In addition, LOXL2 has been associated with pancreatic cancer pathology and tumorigenicity." (PMID 27285767, 2016). "Both N-WASP and LOXL2 depletion significantly reduced the incidence of liver and lung metastatic lesions in orthotopic mouse models of pancreatic cancer." (PMID 38560567, 2024). "Recently, we reported that lysyl oxidase-like 2 (LOXL2) is important for regulating EMT in pancreatic cancer." (PMID 38560567, 2024). "Our previous study showed that LOXL2 expression levels were higher in human pancreatic cancer cells than in cells of normal pancreas." (PMID 38560567, 2024). "We identified a specific mechanism for inducing LOXL2 overexpression in gemcitabine-resistant pancreatic cancer." (PMID 37737908, 2023). "LOXL2 inhibits tumor growth of gemcitabine-resistant pancreatic cancer cells and increases the sensitivity to gemcitabine in mouse models." (PMID 37737908, 2023). "Gemcitabine-resistant pancreatic cancer exhibits cancer stemness, which is regulated by LOXL2 and is achieved through the regulation of EPCAM and oct4, c-myc by MAPK signaling." (PMID 37737908, 2023). "We found that LOXL2 is highly expressed in gemcitabine-resistant pancreatic cancers compared to the gemcitabine-sensitive by examining both pancreatic patients and pancreatic cancer cells." (PMID 37737908, 2023). "This study investigated the regulatory role of the LOXL2 subfactors in maintaining drug resistance in gemcitabine-resistant pancreatic cancer and aimed to elucidate the induction mechanism leading to LOXL2 overexpression." (PMID 37737908, 2023). "Meanwhile, pancreatic cancer cells also produce enzymes to promote matrix protein cross-linking in ECM such as lysyl oxidase-like protein 2 (LOXL2)." (PMID 37033960, 2023). "Total RNA was isolated from tissues of patients with pancreatic cancer and the difference in LOXL2 expression was compared." (PMID 37737908, 2023). "Expression of LOXL2 in pancreatic cancer activates epithelial to mesenchymal transition (EMT)-induced signals and induces changes in EMT, affecting invasiveness." (PMID 37737908, 2023). "Lysyl oxide-like 2 (LOXL2) is highly expressed in pancreatic cancer and is involved in carcinogenesis and EMT regulation." (PMID 37737908, 2023). "Salidroside is isolated from Rhodiola rosea and reduces HIF-1α and LOXL2 expression levels in the human pancreatic cancer cell line BxPC-3, inhibiting its proliferation and invasion under hypoxia." (PMID 37762708, 2023). "Pre-clinical and clinical data on pancreatic cancer has shown that LOXL2 is correlated with the invasiveness of pancreatic cancer and has the potential to be used as an independent prognostic marker and therapeutic target." (PMID 36465388, 2022). "In the current study, the expression of LOXL2 was higher in human pancreatic cancer tissues than in normal tissues, which highly correlated to the tumor stage." (PMID 35433829, 2022). "These genes particularly LOXL2 are overexpressed in pancreatic cancer and the competent function of miR-29a can downregulate the expression of these oncogenes and decrease pancreatic cancer growth." (PMID 34978469, 2022).